GLI1 (GLI family zinc finger 1)
Diseases named in the same sentence as GLI1 in open-access papers (continued):
Sharing a sentence is not in itself a finding about the gene and the disease.
mesenchymal tumors (continued). "Based on the morphological and immunophenotypic characteristics, molecular studies confirmed the diagnosis of a GLI1-altered mesenchymal tumor." (PMID 39995845, 2025). "We have compiled data from the English literature concerning GLI1-altered mesenchymal tumors that have experienced recurrence and metastasis." (PMID 39995845, 2025). "GLI1-altered mesenchymal tumors represent a rare category of neoplasms, with only 90 cases documented in the English literature to date." (PMID 39995845, 2025). "A pleural nodule was incidentally detected during staging, and biopsy revealed a mesenchymal tumour with a novel NCOR2(exon 7)::GLI1(exon 6) gene fusion." (PMID 41035732, 2025). "In this review, we focus specifically on the GLI1-rearranged enteric tumor, a recent clinicopathological entity that has emerged within the expanding classification of mesenchymal tumors." (PMID 39851545, 2025). "We report a rare case of a pleural-based GLI1-altered mesenchymal tumour with a previously undescribed NCOR2::GLI1 gene fusion and unusual SOX10 positivity in a young adult with synchronous colorectal adenocarcinoma." (PMID 41035732, 2025). "We conducted a literature review and were not able to find any publication of SSTR2A immunohistochemical positivity in GLI1-altered mesenchymal tumors." (PMID 39720383, 2024). "Other differential diagnoses of GLI1-altered mesenchymal tumors include glomus tumor, myoepithelial tumor and epithelioid schwannoma." (PMID 39720383, 2024). "GLI1-altered mesenchymal tumors occur in various anatomic locations, with the head and neck region being one of the more commonly reported sites of these tumors." (PMID 39720383, 2024). "GLI1 amplification and gene fusions have been identified in multiple mesenchymal neoplasms and an emerging class of GLI1-altered mesenchymal tumors." (PMID 39062853, 2024). "GLI1-altered mesenchymal tumors have been reported in a variety of anatomic locations, with tumors in the soft tissue, head and neck, trunk, and extremities being the most common." (PMID 39720383, 2024). "GLI1 immunostaining shows high specificity and good sensitivity for GLI1-rearranged mesenchymal tumors." (PMID 38217715, 2024). "The mass was excised and measured 6.3 cm in the greatest dimension, with histologic findings and molecular workup confirming the diagnosis of a GLI1-altered mesenchymal tumor with beta-acting gene (ACTB) fusion." (PMID 39720383, 2024). "The diagnosis of GLI1-altered mesenchymal tumor was established." (PMID 41888999, 2026). "While surgical excision remains the gold standard for treating glomus tumors, GLI1‐altered mesenchymal tumors could respond to targeted therapies, particularly those inhibiting the Hedgehog signaling pathway." (PMID 39776317, 2025). "Furthermore, the strong and diffuse cytokeratin expression in this case seemed unusual for a GLI1-altered mesenchymal neoplasm." (PMID 40248085, 2025). "Surgery serves as the primary treatment for GLI1-altered mesenchymal tumors, while inhibitors of the sonic hedgehog signaling pathway may offer potential targeted therapy for tumors exhibiting GLI1 activation." (PMID 39995845, 2025). "We present the first documented case of a GLI1-altered mesenchymal tumor occurring in the pleura." (PMID 39995845, 2025). "The novel SSTR2A immunopositivity in our case is of uncertain significance at this point in time as more cases of GLI1-altered mesenchymal tumors will need to be examined for this protein expression to draw conclusions about its potential therapeutic or clinical outcome." (PMID 39720383, 2024). "GLI1-altered mesenchymal tumors typically stain positive for CD56 and S100." (PMID 39720383, 2024). "In addition, GLI1 immunostaining shows high specificity and good sensitivity for GLI1-rearranged mesenchymal tumors." (PMID 38491228, 2024). "Thus, a GLI1-altered mesenchymal tumor should be included in the differential in any neoplasm in the head and neck that stains positively for SSTR2A." (PMID 39720383, 2024).
mesenchymal tumors (continued). "GLI1-altered mesenchymal tumors are a recently described emerging entity." (PMID 39720383, 2024). "GLI1-altered mesenchymal tumors are soft tissue tumors that arise in many regions of the body." (PMID 39720383, 2024). "GLI1-altered neoplasms may exhibit morphological overlap with certain mesenchymal neoplasms and may also have coamplification of neighboring genes, depending on the amplicon length." (PMID 38275873, 2024). "GLI1-altered soft tissue neoplasms are recently described mesenchymal tumors of uncertain histogenesis, characterized by epithelioid or glomoid (and less frequently focally spindled) morphology and non-specific immunoprofile, presenting in the head and neck in 40% of cases." (PMID 38491228, 2024). "Notably, SOX10 expression is atypical for GLI1-altered mesenchymal tumours." (PMID 41035732, 2025). "This class of mesenchymal tumors comprises a wide array of molecular alterations, with the most common being GLI1::ACTB, GLI1::PTCH1 or GLI1::MALAT1." (PMID 39720383, 2024). "A case of GLI1-altered mesenchymal tumour with NCOR2(exon 1)::GLI1(exon 4) fusion has been reported, which showed no recurrent disease at 4 months follow-up." (PMID 41035732, 2025). "Somatostatin receptor 2A (SSTR2A) immunopositivity has not been reported to date in GLI1-altered mesenchymal tumors." (PMID 39720383, 2024). "Herein, we report a GLI1-altered mesenchymal tumor with ACTB fusion and unique immunohistochemical staining for SSTR2A and will discuss how this staining can impact the differential diagnosis of GLI1-altered mesenchymal tumors." (PMID 39720383, 2024). "GLI1-altered mesenchymal tumors exhibit non-specific immunohistochemical characteristics." (PMID 39995845, 2025). "However, in this case, GLI1 IHC was focally and weakly positive rather than diffusely and strongly positive, which does not positively support a GLI1-altered mesenchymal neoplasm." (PMID 40248085, 2025). "Given that the Hedgehog pathway has been shown to control the development of the mouse gut mesenchyme, we sought to determine whether two commonly studied murine models of the mesenchymal tumor GIST express key Hedgehog signaling components (Shh, Ihh, Ptch1, Smo, Gli1, Gli2, Gli3)." (PMID 27793025, 2016).
sarcoma (13 papers, 2010 to 2026). A usually aggressive malignant neoplasm of the soft tissue or bone. "GLI1-rearranged enteric tumors exhibit behaviors that are similar to those of low-grade to intermediate-grade sarcomas." (PMID 39851545, 2025). "In sarcomas, including ES, aberrant Hh signaling is thought to be due to increased expression of GLI1, SMO, and PTCH132." (PMID 39894896, 2025). "We found evidence for HH pathway activity and GLI1 expression in RMS and EWS cell lines at baseline, and evidence that GLI1 contributes to survival and proliferation of these sarcoma cells." (PMID 32493277, 2020). "GLI1 amplification was reported in childhood sarcomas but the frequency varies considerably among different types of sarcomas." (PMID 21119888, 2010). "Notably, capillary-sized blood vessels were present throughout the tumor, which made BCOR-rearranged sarcomas, myxoid liposarcoma with small cell morphology, and GLI1-altered soft tissue tumors the main differential diagnoses." (PMID 40791569, 2025). "We hypothesize that the combination of BCOR and GLI1 expression in SSs could predict biological behavior and may provide a possible opportunity as a therapeutic target in these high-grade sarcomas." (PMID 39062853, 2024). "Although we did not see effects of SHH exposure on cell viability or proliferation, we did see increased apoptosis in RMS and EWS cells and reduced viability and proliferation in EWS cells with GANT61 treatment, suggesting fundamental roles for GLI1 in the biology of these sarcoma cell lines." (PMID 32493277, 2020). "Genes including Wnt 4 and 5a, beta-catenin, LEF1, and RhoA in Wnt-signaling pathways showed significantly lower expression and DKK1, a Wnt signal inhibitor showed strong expression in both sarcomas, while those in Hedgehog pathways showed higher expression in both sarcomas, especially Gli1." (PMID 22852096, 2012). "Additionally, GLI1 immunostains can be utilized as well, however caution must be taken as GLI1 gene amplification is seen in a number of sarcomas and carcinomas leading to GLI1 protein overexpression and positive immunostaining which may lead to potential diagnostic pitfalls." (PMID 39720383, 2024). "FISH techniques can also be applied to distinguish GLI fusion tumors from other carcinomas and sarcomas that exhibit MALAT1 rearrangement without GLI1 involvement." (PMID 39851545, 2025).
triple-negative breast carcinoma (13 papers, 2013 to 2024). An invasive breast carcinoma which is negative for expression of estrogen receptor (ER), progesterone receptor (PR), and human epidermal growth factor receptor 2 (HER2). "Its role in bladder and triple negative breast cancer stemness and tumorigenesis, was reviewed, and the prognostic value of glioma-associated oncogene (Gli1), an essential mediator of this pathway, was emphasized." (PMID 35873564, 2022). "Vascular endothelial growth factor (VEGF)/neuropilin-2 (NRP2)/GLI family zinc finger 1 (GLI1) signaling suppressed ESRP1 expression via transcription repressor polycomb complex protein BMI1 in triple-negative breast cancer cell lines." (PMID 38110955, 2023). "Combined treatment with chemotherapy, Notch inhibitor, and GLI1 inhibitor blocks African American (AA)-triple negative breast cancer (TNBC) tumor progression." (PMID 34889737, 2021). "In the M6-Hh (Hh expressing murine triple-negative breast cancer) tumors, Shh expressed from tumor epithelium cells induced expression of GLI1 in CAFs of the surrounding stroma, resulting in their activation." (PMID 34572373, 2021). "GLI1 and Notch1 pathways are upregulated in African American (AA)-triple negative breast cancer (TNBC) in comparison to White American (WA)-TNBC." (PMID 34889737, 2021). "Inhibition of Notch and GLI1 enhances the effect of carboplatin in African American (AA)-triple negative breast cancer (TNBC); Notch1 and GLI1 are overexpressed in AA-TNBC tissues in comparison to TNBC tissues from White American (WA) women." (PMID 34889737, 2021). "In the present study, CDDO-Im decreased both mRNA and protein level of GLI1 in tumorspheres of triple-negative breast cancer." (PMID 25229616, 2014). "We preliminarily confirmed that the mitochondrial outer membrane protein FUNDC2 may promote the development of triple-negative breast cancer through the AKT/GSK3β/GLI1 signaling axis." (PMID 37700593, 2023). "Moreover, a recent study demonstrated that GLI1 was a central regulator of cancer stem cells in triple-negative breast cancer." (PMID 25229616, 2014). "Moreover, smoothened homolog (SMO) and GLI1 were highly expressed in triple negative breast cancer, and their increased expression was correlated with metastasis, poor prognosis, and recurrence of triple negative breast cancer." (PMID 36701089, 2023). "Concomitant upregulation, co-localization, and interaction of GLI1 and Notch intracellular domain (NICD) in African American (AA)-triple negative breast cancer (TNBC)." (PMID 34889737, 2021). "Also, tGLI1 was found to be exclusively elevated in patients having triple negative breast cancer as opposed to GLI1 which was active in luminal B subtype as well." (PMID 31036836, 2019). "In addition to the previous report that integrin α6β1-activated FAK induces GLI-1 expression in triple-negative breast cancer, our present results with ITGA11 KD demonstrated that integrin α11 induced activation (nuclear translocation) of GLI-1, but not HIF1α and EZH2." (PMID 38664825, 2024).
brain tumor (12 papers, 2009 to 2024). "AMPK has been shown to directly phosphorylate and destabilize GLI1 in brain tumor cells, whereas mTORC1 activation (through S6K1) has been shown to phosphorylate GLI1 in esophageal cells and increase its nuclear translocation." (PMID 34203724, 2021). "Immunohistochemistry (IHC) staining showed that Gli1 was highly expressed in mice xenograft brain tumors, which further demonstrated that SMO-193a.a." (PMID 33446260, 2021). "Overexpression of the GLI1 gene has frequently been found in various cancer types, particularly in brain tumors, in which aberrant GLI1 induction promotes cancer cell growth." (PMID 28562331, 2017). "In a panel of clinical brain tumor specimens, variable expression of Shh, Patched, and Gli1 was found, with Gli1 overexpressed on average in all tumors when compared to normal brain tissue." (PMID 24212632, 2011). "In addition, the simultaneous blockade of Gli1 and lactate efflux amplifies the anti-tumor effect in vivo, providing new potential therapeutic strategy for this brain tumor." (PMID 31455353, 2019). "Indeed, PCAF acts as a transcriptional cofactor of GLI1 in permissive conditions by increasing H3K9 acetylation at GLI target gene promoters, leading to brain tumor cell growth." (PMID 31244888, 2019). "In addition, there is an inverse correlation between phosphor-AMPK and GLI1 protein expression levels in a cohort of brain tumor tissues." (PMID 28562331, 2017). "Currently, in a cohort of 198 brain tumors, we found that p-AMPK (the active form of AMPK) protein expression levels are inversely correlated with GLI1 as shown in the representative MB cases." (PMID 28562331, 2017). "In agreement with in vitro observations, penfluridol treatment reduced pAkt(Ser473), GLI1 and OCT4, and enhanced cleavage of caspase 3 in brain tumors." (PMID 28380428, 2017).
skin tumors (10 papers, 2011 to 2025). "For example, mice overexpressing Gli1 in skin epidermis (K5-Gli1) develop several types of skin tumors, primarily hair follicle-derived tumors and BCCs, whereas Gli2 overexpression (K5-Gli2) only causes the formation of BCCs." (PMID 31438551, 2019). "Immunohistochemical evaluation of the HH-related molecules demonstrated that only GLI1 protein had the same expression pattern as its mRNA in skin tumors." (PMID 31756206, 2019). "Furthermore, when compared with BCC or SCC tumors at three different tumoral stages, the expression of Gli-1, Ptch-1, K8, and K17 was elevated in RTHα skin nevi but to a lesser extent than that observed in the skin tumors." (PMID 33509032, 2021). "In addition to BCCs, which arises in mice expressing GLI1 in the skin, these mice also develop cylindroma and trichoepitheliomas, suggesting that the loss or inactivation of CYLD in different skin cancer diseases can affect the same signaling pathway." (PMID 22235375, 2011). "In tumor cell lines, bone tumors displayed the highest expression of both GLI1 and GLI2, whereas skin tumor cell lines exhibited the greatest expression of GLI3." (PMID 38498906, 2024). "Although several reports have specifically shown GLI1 expression in human BCCs, no study has thoroughly examined the expression of multiple HH-related molecules in a variety of human skin neoplasms." (PMID 31756206, 2019).
squamous cell carcinoma (10 papers, 2013 to 2024). A carcinoma arising from squamous epithelial cells. "GLI1 expression level predicts poor outcomes in patients diagnosed with squamous cell carcinoma." (PMID 37149646, 2023). "We found that vismodegib decreases expression of the Hedgehog target genes glioma-associated oncogene homologue (GLI1) and the inhibitor of apoptosis protein (IAP) Survivin in a cell line- and irradiation-dependent manner, most pronounced in squamous cell carcinoma (SCC) cells." (PMID 30142876, 2018).
acute promyelocytic leukemia (9 papers, 2015 to 2023). An aggressive form of acute myeloid leukemia (AML), characterized by arrest of leukocyte differentiation at the promyelocyte stage, due to a specific chromosomal translocation t(15;17) in myeloid cells. "For example, arsenic trioxide, known for its activity in acute promyelocytic leukemia, was recently found to inhibit the transcription of GLI1 and induce apoptosis of CLL cells." (PMID 33747356, 2021). "For example, SHH activates downstream transcription factor GLI-1 in several hematological malignancies, with prevalent expression observed in AML and acute promyelocytic leukemia (APL) patients." (PMID 26483188, 2015). "The precise mechanism by which arsenic trioxide, which is FDA approved for acute promyelocytic leukemia, inhibits GLI1/2 is not known." (PMID 36010600, 2022). "Interestingly, arsenic trioxide, which is an FDA-approved inhibitor of GLI1 and GLI2 transcription factors, is used as a single agent against acute promyelocytic leukemia." (PMID 35406554, 2022).
bladder cancer (9 papers, 2010 to 2025). "Here, we show that adipocyte enhancer binding protein 1 (AEBP1) attenuates the dependency of bladder cancer cell survival on the FACT complex via the expression of GLI1, a pivotal transcription factor in Hedgehog signaling." (PMID 40612002, 2025). "The result showed that iG2 strongly inhibited the expression of Hh pathway transcriptional factors Gli1 and Gli2, as well as the downstream protein Jag2 in primary bladder cancer cells." (PMID 27465044, 2016). "The iG2 can strongly downregulated the expression of Gli1, Gli2, and downstream Jag2 genes in bladder cancer cells." (PMID 27465044, 2016). "Protein expression of SHH, PTCH and GLI1 were all independent prognostic factors for both disease-free survival and overall survival in patients with colon cancer and bladder cancer." (PMID 26053182, 2015). "We speculated that PC deficiency due to STIL overexpression could inhibit the activated form of SMO and induce the activated form of GLI1 to promote tumorigenesis in bladder cancer." (PMID 37101292, 2023). "In the current study, we demonstrated that knockdown of ROC1 expression inhibited Gli2 expression but not Gli1 expression, whereas ROC1 overexpression promoted Gli2 expression in bladder cancer cells." (PMID 33499884, 2021).